MIR142HG (MIR142 host genes)
Gene: Long non-coding RNA gene on chromosome 17 (58,330,879 to 58,332,524, reverse strand). Ensembl gene ENSG00000265206.
Gene Ontology:
Biological process: miRNA-mediated post-transcriptional gene silencing
Cellular component: RISC complex
Diseases named in the same sentence as MIR142HG in open-access papers:
MIR142HG is named in the same sentence as 2 diseases in open-access papers, as found by Europe PMC text mining. Sharing a sentence is not in itself a finding about the gene and the disease. The quoted sentences say what the papers report.
glioma (1 paper, 2025). A benign or malignant brain and spinal cord tumor that arises from glial cells (astrocytes, oligodendrocytes, ependymal cells). "However, the expression levels of Neat1, Mir142hg, Pvt1, Mir17hg, SNHG12 and Meg3 showed opposite trends, which may correlate with the distinct inflammatory profiles and immunophenotypes of the different glioma models analyzed." (PMID 40527978, 2025).
cancer (1 paper, 2025). A tumor composed of atypical neoplastic, often pleomorphic cells that invade other tissues. "Notably, MEG3, MIAT, Malat1, SNHG20, SNHG12, Ftx, Pvt1, Mir9-3hg expression in cancer immune cells was associated with an immunosuppressive phenotype, while H19, SNHG6, Trp53cor1, MiR17hg and MiR142hg were linked to a pro-inflammatory phenotype in cancer." (PMID 40527978, 2025).